CXCR5 (C-X-C motif chemokine receptor 5)
Diseases named in the same sentence as CXCR5 in open-access papers (continued):
Sharing a sentence is not in itself a finding about the gene and the disease.
tumor (continued). "In parallel to these functions, CXCL13 plays a key role in promoting immune infiltration in the tumor via binding to CXCR5 and controlling tumor behavior by binding to receptors on the tumor surface." (PMID 34445452, 2021). "Tumor load in the BM was profoundly reduced in mice treated with CXCR5 CAR-T cells compared with SP6 CAR-T cells at day 8, and in BM and spleen at day 13 as well." (PMID 33431832, 2021). "We also observed a significant increase in CXCR5+ B cells in vaccinated mice compared to controls suggesting that B-lymphocytes had migrated to tumor sites as a result of our treatment." (PMID 34957134, 2021). "Due to the complexities of the CXCL13/CXCR5 axis in tumor milieu, CXCR5 expression status on tumor cells should be carefully assessed in clinical practice." (PMID 35693216, 2021). "In most cancer types, the CXCL13/CXCR5 axis mediates pro-neoplastic immune reactions by recruiting suppressive immune cells into tumor tissues." (PMID 34947813, 2021). "The exhaustion markers PD-1, LAG-3, and TIM-3 were not differentially upregulated over 13 days on BM or splenic localized CD4+ and CD8+ CXCR5 CAR-T compared to SP6 CAR-T cells, thus exhaustion seems to be unlikely involved in loss of tumor control." (PMID 33431832, 2021). "Another study demonstrated that CXCL13, which is regulated by interferon regulatory factor 5 (IRF5), mediates CXCR5+ B cells and T cells homing to tumors, thereby eliciting an anti-tumor immune response." (PMID 34947813, 2021). "Over the course of the experiment, 4–5 mice per time point were analyzed for tumor load, CXCR5 expression of tumor cells, and total CD4 and CD8 T cell numbers in BM and spleen." (PMID 33431832, 2021). "Stem-like PD-1loCD8+ TILs have been found to sporadically express CXCR5 depending on the tumor type." (PMID 34354714, 2021). "At the moment, various novel approaches are being employed to inhibit CXCL13/CXCR5 signaling in the tumor microenvironment." (PMID 34922542, 2021). "Taken together, CXCL13 and CXCR5 usually act as oncogenic cascades in the promotion of tumor cell survival, proliferation, migration, and invasion, and represent therapeutic targets for the development of novel anti-cancer drugs." (PMID 34947813, 2021). "Peptides were added at increasing concentrations to a co-culture of JeKo-1 tumor cells with CXCR5 or CD19 CAR-T cells." (PMID 33431832, 2021). "The CXCL13/CXCR5 axis plays pivotal roles in the dissemination and accumulation of malignant lymphocytic cells and in shaping such a tumor-stromal cell microenvironment interaction network." (PMID 34947813, 2021). "Patients with CXCR5+CD8+T-high tumor have superior OS than patients with CXCR5+CD8+T-low tumor in the MSI-low/MSS, MSI-high, and EBV-negative subgroups (P < 0.001, P = 0.006, and P = 0.034, respectively)." (PMID 34035252, 2021). "Tfh cells (CD4+PD1+CXCR5+) can exhibit a tumor-supporting role in human B cell malignancies, foremost in FL and CLL18." (PMID 33431832, 2021). "Chemotactic CAR-T cells show superior trafficking toward tumor sites and enhanced cytotoxicity: a proof of concept study of CXCR5-EGFR-CAR-T for the CXCL13+ NSCLC tumor." (PMID 34553036, 2021). "Mounting evidence demonstrates a high concentration of CXCL13 and/or high expression of CXCR5 in tumor tissues or tumor cell lines." (PMID 34947813, 2021). "As a chemokine, CXCL13 binds to its homologous receptor CXCR5, participates in the migration and recruitment of lymphocytes, which helps to enhance the immune response of tumor host." (PMID 34736480, 2021). "B cells homing into the TME via the CXCL13/CXCR5 axis include pro-tumor B cells and anti-tumor B cells." (PMID 34947813, 2021). "Further univariate Cox analyses reveal that patients with MSI-low/MSS and CXCR5+CD8+T-low tumor or patients with EBV-negative and CXCR5+CD8+T-low tumor have worst outcome." (PMID 34035252, 2021).
tumor (continued). "The roles of the CXCL13/CXCR5 axis participating in the malignant tumors are context-dependent, including pro-tumor and anti-tumor activities." (PMID 34947813, 2021). "In this study, prompted by the observation of the CXCL13 overexpression on certain NSCLC patients, we implemented the strategy to co-express CXCR5 with the anti-EGFR-CAR-T to facilitate T cell migration to the tumor site." (PMID 34553036, 2021). "Specifically, we observed a significant increase in CXCR5+ B cells in vaccinated mice as compared to controls, suggesting that B-lymphocytes had migrated to tumor sites as a result of the combined therapy." (PMID 34957134, 2021). "And patients with tumor, node, metastasis (TNM) II + III disease whose tumor with higher CXCR5+CD8+T cell infiltration can benefit more from adjuvant chemotherapy (ACT)." (PMID 34035252, 2021). "Taken together, the present study demonstrated that CXCR5 triggered the differentiation of tumor cells into Schwann-like cells through repressing miR-187 to disinhibit S100A4, thus facilitating PNI of SACC." (PMID 34114971, 2021). "In these settings they have been reported to exhibit stem-like properties, presenting as promising targets for anti-PD-1 therapy and displaying superior anti-tumour functionality compared to their CXCR5- counterparts." (PMID 34326833, 2021). "A recent study indicated the presence of CD8+CXCR5+ T cells in FL and proposes that this functional subset mediates anti-tumor activity." (PMID 33431832, 2021). "Anti-murine CXCR5 CAR-T cells exhibit potent anti-tumor activity in vitro, and most importantly, facilitate specific benign and malignant B and CXCR5+ Tfh cell depletion without further off-target activity in a syngeneic mouse model." (PMID 33431832, 2021). "To integrate tumor microenvironment characteristics and molecular subtypes, we sought to determine the association between CD8+T/CXCR5+CD8+T and TCGA/ACRG classifications." (PMID 34035252, 2021). "The CXCL13/CXCR5 axis plays multifaceted roles in intracellular signaling transduction pathways and interactions among tumor cells, stromal cells, and lymphocytes." (PMID 34947813, 2021). "Although ELR− CXC chemokines belong to the antiangiogenic CXC chemokine family, ELR− CXC chemokines, including CXCR3, CXCR4, CXCR5, CXCR6, and CXCR7, are associated with tumor growth, proliferation, and metastasis in PC." (PMID 33195424, 2020). "CXCL13, and its receptor, CXCR5 (CXCL13/CXCR5 axis), serve as an important pathway of tumor proliferation and metastasis 47-49." (PMID 32669964, 2020). "As in the case of CXCL9, IRF5 (interferon regulatory factor 5) can bind to the promoter of CXCL13 and directly regulate its expression in mammary epithelial tumor cells leading to the infiltration of CD19+CXCR5+ B-cell and CD4+CXCR5+ T-cell to the tumor." (PMID 33304345, 2020). "Targeted delivery of CpG-ODN to CXCR5 expressing cells, reversed the phenotype of these tumour evoked Bregs (which upregulated CD20) and restored effector B-cell responses." (PMID 31901949, 2020). "Yet, tumor-infiltrating and virus-specific CXCR5+ CD8 T cells appear to maintain cytolytic capacity upon ex vivo stimulation." (PMID 31275308, 2019). "The elucidation of CXCR5 signaling effectors and target genes would help profiling molecular scenarios controlling tumor development and its response to targeted therapies." (PMID 31354634, 2019). "We found that the frequency of IL-21-producing CD8+CXCR5+ T cells was higher in HCC tumor tissue than in peritumoral tissue or peripheral blood from the same patients or in blood from healthy donors." (PMID 31663864, 2019). "Yet, combined blockade of Tim-3 and PD-1 augment CXCR5+ CD8 T cell specific lysis of tumor cell targets indicating reduced lytic potential." (PMID 31275308, 2019). "Our results show that CD8+CXCR5+ T cells strongly infiltrate the tumor tissue and play a key role in the HCC-directed antitumor immune response." (PMID 31663864, 2019).
tumor (continued). "In spite of the fairly robust cytolytic potential and activity by CXCR5+ CD8 T cells, tumor cells likely employ inhibitory mechanisms to suppress CXCR5+ CD8 T cell function." (PMID 31275308, 2019). "We demonstrated that large numbers of IL-21-producing CD8+CXCR5+ T cells accumulate within HCC tumor tissue." (PMID 31663864, 2019). "The CXCR5 axis is generally considered to have tumor suppressor properties, and its stimulation has been proposed as a means of combating cancer." (PMID 31781492, 2019). "In the present study, therefore, we examined CD8+CXCR5+ T cells found within matched tumor tissue, peritumoral tissue, and peripheral blood from HCC patients." (PMID 31663864, 2019). "IL-10 or PD-1L blockade induced CXCR5+ CD8 T cell targeted specific cell lysis of autologous tumor cells." (PMID 31275308, 2019). "In HCC patients, the percentage of CD8+CXCR5+ T cells was obviously larger in tumor tissue than in the peritumoral liver or blood." (PMID 31663864, 2019). "Because IL-21 plays a critical role in regulating immunoglobulin production, we investigated the possible effects of tumor-infiltrating CD8+CXCR5+ T cells on B cells." (PMID 31663864, 2019). "CXCR5+ CD8 T cells isolated during immune responses to cancer maintain cytolytic potential toward tumor cells despite protein expression typically indicative of exhaustion." (PMID 31275308, 2019). "Current evidence also indicates that the CXCL13:CXCR5 axis orchestrates cell-cell interactions that regulate lymphocyte infiltration within the tumor microenvironment, thereby determining responsiveness to cytotoxic and immune-targeted therapies." (PMID 31354634, 2019). "In summary, we observed first that strong infiltration of CD8+CXCR5+ T cells into HCC tumor tissue reduces the likelihood of recurrence." (PMID 31663864, 2019). "Patients with high tumor grade have an elevated percentage of CD4+CXCR5+ T-cells compared to those with low tumor grade." (PMID 31354634, 2019). "Precursor populations of exhausted tumor-infiltrating T cells with higher TCF-1 and CXCR5 expression were also identified to be linked to better clinical outcomes after checkpoint blockade therapy." (PMID 32038613, 2019). "We subsequently found that strong tumor infiltration by IL-21-producing CD8+CXCR5+ T cells led to the accumulation of IL-21+ cells within the peritumoral stroma and that this accumulation correlated negatively with the TNM staging of the patients." (PMID 31663864, 2019). "CXCL13, the corresponding ligand for CXCR5, has been detected in tumor cells, dendritic cells, and T follicular helper cells as well as stromal cells in B cell follicles." (PMID 31663864, 2019). "We found that numbers of IL-21-producing CD8+CXCR5+ T cells were significantly higher within HCC tumor tissue than in the matched blood and peritumoral liver tissue or in healthy blood samples." (PMID 31663864, 2019). "Enhancing specific cell lysis by preventing tumor suppression of CXCR5+ CD8 T cells or by improved CXCR5+ CD8 T cell function provides a new potential target for existing cancer therapeutics." (PMID 31275308, 2019). "We found that IL-21-producing CD8+CXCR5+ T cells strongly infiltrate HCC tumor tissue as compared to peritumoral tissue or peripheral blood from the same patients or blood from healthy donors." (PMID 31663864, 2019). "Programmed cell death 1 is considered to be an exhaustion marker expressed on CD8+ T cells during chronic infection or tumor progression; however, PD-1 expression on CXCR5+CD8+ T cells during chronic HIV infection remains poorly defined." (PMID 29312314, 2017). "To investigate the role of CD40 in CXCR5 expression regulation, we compared CXCR5 expression in bone marrow and tumor tissues from the MDSC of WT and KO mice." (PMID 26462153, 2015).
tumor (continued). "Consistently, the tumor volume of Cxcr5-/- mice was significantly lower than Cxcr5+/- and Cxcr5+/+ mice." (PMID 26565418, 2015). "In the poorly differentiated group, both CXCL13 and CXCR5 were remarkably higher in tumor tissues, indicating that CXCL13 was regionally increased in poorly differentiated HCC tumor tissues." (PMID 26517519, 2015). "Characterization of tumor-infiltrating CXCR5+CD45RA−CD4+ T cells in 12 pairs of matched tumor and para-tumor tissues showed that the population of CXCR5+CD45RA− cells among CD4+ T cells was higher in tumor tissues than in para-tumor tissues (P = 0.012)." (PMID 26517519, 2015). "Actually, numerous chemoattractant GPCRs, such as CCR1, CCR5, CXCR5, CXCR7, and PAFR, are expressed by various types of tumor cells and are implicated in tumor growth." (PMID 25110692, 2014). "Blocking CXCR5 on 2F7 cells with neutralizing antibodies prior to injection into the mice substantially delayed tumor formation." (PMID 23936541, 2013). "In several of these cancers, tumor cells were shown to express functional CXCR5 and to migrate towards CXCL13." (PMID 21490903, 2010). "However, in many cancer types, the CXCL13/CXCR5 axis also promotes the recruitment of immunosuppressive cells to the tumour site." (PMID 40361472, 2025). "CXCL13 colocalizing with TLSs shapes anti-tumor microenvironment by maintenance of CXCR5+CD8+ T cells in TLS.TLS prognostic benefit is only relevant in the presence of CXCL13.High CXCL13 expression associated with prolonged survival.Supports a new CXCL13 & PD-1 blockade clinical trial in HGSOC." (PMID 40475770, 2025). "The role of CXCL13 as a potential importance in CRC therapy has been confirmed by other investigators, who also revealed that CXCL13/CXCR5 axis may target tumors by recruiting B lymphocytes, and is essential in the anti-tumor immune response of TME in CRC." (PMID 40943634, 2025). "Expression analysis of key regulators of cell migration (CXCR3, CCR7, CXCR5 and ITGAL, which encodes LFA1, an alias protein name) within these groups revealed significant upregulation of CCR7 in a subset of tumor-infiltrating SH2D2A-positive T cells and CXCR3 in infiltrating SH2D2A-positive T cells." (PMID 41394860, 2025). "However, patients with CXCR5 expression on tumor-infiltrating lymphocytes had a better outcome compared to those without." (PMID 39001456, 2024). "Our findings revealed that CXCR5 expression was markedly low in all tumor and normal clusters." (PMID 39344390, 2024). "CXCR5 is expressed significantly in B cells, Tfh cells, mature DCs, and tumor cells." (PMID 39840050, 2024). "Furthermore, the specific high expression of CXCL13 and CXCR5 in PD1+CD4+ T cells was observed in tumour tissues as well as adjacent tissues." (PMID 36855810, 2023). "Among 28 chemokine genes available, CXCL9/10/11/CXCR3, CXCL13/CXCR5 and XCL1/XCR1 mRNA expression were significantly increased in RCC compared to normal kidney tissue and also strongly associated with tumor-infiltrating effector memory and central memory CD8+ T cells in all investigated collectives." (PMID 37006314, 2023). "Notably, CXCR5 frequency increased in all subsets with the transition to the tumor, maintaining the highest expression in PD1+CD28+ cells." (PMID 37898752, 2023). "However, the function of the CCL19, CCL21/CCR7 and CXCL13/CXCR5 axes in tumor immunity is complicated." (PMID 37215990, 2023). "We propose a model where an effective response to ICI is marked with CXCL13+ CD8 T cell-driven recruitment of highly diversified, CXCR5+ B cell clones whose subsequent (tumor) antigen presentation activities induce and sustain the activation of tumor-reactive CD4 Tfh and CD8 T cells." (PMID 37435085, 2023). "Similarly, IL-21 producing CXCR5+ CD8 T cells accumulate in the hepatocellular carcinoma tumor tissues in close proximity to CD19+ B cells, which predicts better disease prognosis." (PMID 36172358, 2022).
tumor (continued). "Accordingly, CXCL13 produced by CXCR5+/CD8+ TILs (through autocrine, paracrine or endocrine) might directly bind and induce cytotoxicity to lyse CXCR5+ tumor cells." (PMID 35392977, 2022). "How CXCR5+CD8 T cells affect the tumor microenvironment, B cell infiltration, autoantibody response, T cell tissue residency, and peripheral organ involvement after ICB remains unknown." (PMID 36314014, 2022). "Elucidating CXCL13/CXCR5 signaling effects and downstream signaling pathways will help investigate the molecular mechanisms that control tumor progression and responses to targeted therapies, accelerating the translation of drug research into clinical precision medicine." (PMID 35702353, 2022). "Increased CXCL13 within the tumor microenvironment may further facilitate immunosuppression due to increased recruitment of CXCR5-expressing regulatory T (Treg) cells." (PMID 36217194, 2022). "CXC chemokine ligand 13 (CXCL13) is an important factor involved in recruiting immune cells that express CXC chemokine receptor type 5 (CXCR5) in the tumor microenvironment and serves as a key molecular determinant of tertiary lymphoid structure (TLS) formation." (PMID 35053457, 2022). "In summary, the abundance of intratumoral CXCR5+CD8+T is associated with better OS and patients with TNM II + III disease whose tumor presented higher intratumoral CXCR5+CD8+T cells could benefit more from ACT." (PMID 34035252, 2021). "Thus, at primary sites of tumor cell homing CXCR5 CAR-T cells were specifically amplified and were detectable up to 13 days after adoptive transfer." (PMID 33431832, 2021). "Also the altered CAR-T cell: tumor cell ratio led to the dysfunction of CXCR5 CAR as well as CD19 CAR-T cells from the third round of stimulation on accompanied by enhanced PD-1 expression on CD8+ and CD4+ CAR-T cells." (PMID 33431832, 2021). "In this study, the co-expression of CXCR5 in CAR-T was designed to not only increase the infiltration of CAR-T cells but also to mitigate potential off-tumor toxicity, due to our results that CAR-T only infiltrates into EGFR and CXCL13 double-positive tumor sites and produces a killing effect." (PMID 34553036, 2021). "The CXCL13/CXCR5 axis shows anti-tumor and pro-tumor functions." (PMID 34947813, 2021). "Next, we compared the anti-tumor activity of the CXCR5 and CD19 CAR-T cells." (PMID 33431832, 2021). "Detailed analysis of tumor‐specific CD8 T‐cell responses may help to determine the presence of CXCR5+PD‐1+Tcf1+ CD8 T cells despite a high background of PD‐1+Tcf1+ memory cells in the same LN tissue." (PMID 33098668, 2021). "The CXCL13/CXCR5 axis not only modulates molecular events inside malignant cells to promote tumor initiation and progression, but also recruits multiple populations of lymphocytes to exert pro-tumor or anti-tumor immunity reactions in the TME." (PMID 34947813, 2021). "The CXCL13/CXCR5 axis is involved in the regulation of cancer cell survival, apoptosis, proliferation, differentiation, migration, invasion, and adaptive immunity, and shows dichotomic anti- and pro-tumor functions in the TME." (PMID 34947813, 2021). "Thus, a better understanding of the context-dependent functions of the CXCL13/CXCR5 axis in tumor tissue and the TME is required to design an efficient immune-based therapy." (PMID 34947813, 2021). "Future studies in hematologic malignancies should analyze CXCR5+PD‐1+ CD8 T cells within tumor‐specific CD8 T‐cell populations during PD‐1 ICB therapy to determine whether CXCR5+PD‐1+ CD8 T cells are a biomarker for therapeutic response." (PMID 33098668, 2021). "Therefore, we further compared PD-1+CXCR5+CD8+T cells with PD1+CD39+CXCR5−CD8+T cells to explore the features of tumor-specific CD8+T cells." (PMID 34035252, 2021). "Overall, the CXCR5 CAR endowed transduced T cells with a robust in vivo anti-tumor activity." (PMID 33431832, 2021).